INS (insulin)
Diseases named in the same sentence as INS in open-access papers (continued):
Sharing a sentence is not in itself a finding about the gene and the disease.
Insulin resistance (continued). "We also calculated various HOMA indices for insulin resistance (HOMA-IR), β-cell function (HOMA-β), insulin sensitivity (HOMA-S), and compensatory β-cell response using a homeostasis model." (PMID 37601212, 2023). "Given the published effects that UCN2 and UCN3 have on insulin signaling, we began by investigating circulating UCN2 and UCN3 levels in established genetic models of insulin resistance." (PMID 37402735, 2023). "Insulin resistance is one of the main pathophysiological underpinnings of T2DM and refers to the reduced response of the body’s cells to insulin, leading to an increase in blood glucose levels." (PMID 37600949, 2023). "Insulin resistance (IR) is tissue‐selective in PCOS patients, as evidenced by the fact that the ovaries and adrenal glands continue to respond to insulin despite skeletal muscles, adipose tissue, and the liver losing their sensitivity to it." (PMID 37985173, 2023). "Individuals with insulin resistance can develop T2DM when pancreatic ß-cells are impaired, and they fail to secrete sufficient insulin to maintain euglycemia." (PMID 36860368, 2023). "Regarding insulin resistance, CTE supplementation significantly increased plasma adiponectin concentrations and reduced the circulating levels of insulin and the HOMA-IR." (PMID 37239868, 2023). "The most commonly used method is the Homeostasis Model Assessment of Insulin Resistance (HOMA-IR) method which is calculated using fasting serum glucose and fasting serum insulin values." (PMID 36874319, 2023). "Fasting blood insulin and ALT levels and HOMA-IR were higher in the obese group, indicating a greater prevalence of insulin resistance and of non-alcoholic fatty liver disease compared to those in the non-obese group." (PMID 37529611, 2023). "Under conditions of insulin resistance, AMPK activation by berberine can increase GLUT4 translocation and glucose transport, thereby increasing glucose consumption and glucose uptake in insulin-resistant H9c2 cells." (PMID 36770960, 2023). "ER stress is the critical mediator in mitochondrial fission-induced insulin resistance in DVC, and relief of ER stress using 4-PBA restores insulin sensitivity in DVC of 3-day HFD rats." (PMID 37174622, 2023). "Insulin resistance is one of the main features of PCOS, characterized by a reduced cellular response to the physiological concentrations of insulin, which triggers a state of hyperinsulinemia." (PMID 37371662, 2023). "This drug also inhibits the transcription of the insulin gene and decreases the expression of glucose transporter GLUT4, resulting in increased insulin resistance." (PMID 37628646, 2023). "It is accepted that an increased FA flux from hypertrophic adipose tissue to insulin-sensitive tissues, which occurs in obesity or DM2, contributes to insulin resistance and glucose intolerance." (PMID 37371984, 2023). "Insulin resistance was assessed using HOMA-IR and altered insulin sensitivity was defined as a HOMA-IR value>97.5th percentile for age, gender and pubertal stage." (PMID 37420288, 2023). "We reported that HFD-fed rats gained more weight and fat mass compared to CD-fed animals and were glucose and insulin intolerant, indicating that HFD feeding indeed induced obesity and insulin resistance." (PMID 37012386, 2023). "Based on these data, we propose exposing 3T3-L1 adipocytes to 0.5 nM insulin and 0.5 ng/ml TNF for 14 h as optimal models of insulin resistance induction." (PMID 36283703, 2023). "The Homeostatic Model Assessment for Insulin Resistance (HOMA-IR) was used to categorize participants as insulin-resistant (HOMA-IR ≥ 2.6) and insulin-sensitive (HOMA-IR < 2.6)." (PMID 37582739, 2023). "Next, we measured insulin signaling in metabolic peripheral tissues with the knowledge that, when exposed to an HFD, mTORKOpl female offspring experience increased insulin resistance and obesity than controls." (PMID 37855320, 2023).
Insulin resistance (continued). "This study explored the efficacy of acupuncture and metformin in enhancing insulin sensitivity among women with polycystic ovary syndrome (PCOS) and insulin resistance (IR), distinguishing between overweight/obese and lean groups." (PMID 38155665, 2023). "PCOS subjects were insulin-resistant, and a 6-month treatment regimen with metformin reduced circulating SAA levels, suggesting a possible link between SAA and adipose tissue insulin sensitivity." (PMID 37396595, 2023). "Under chow conditions, mice with muscle‐specific β‐catenin deletion had impaired insulin responsiveness, whereas under HFD, both mice exhibited similar levels of insulin resistance (interaction effect of genotype × diet p < 0.05)." (PMID 36807886, 2023). "Insofar insulin resistance constitutes on one the most prominent hallmarks of EMS, the potential of SHBG treatment to restore insulin signalling in EMS-affected ASC has been further investigated." (PMID 37697311, 2023). "CRP in the early postpartum predicted higher insulin resistance (higher HOMA-IR, lower MATSUDA) and absolute insulin secretion (HOMA-B and AUCins/glu) but reduced relative insulin secretion (ISSI-2) at 1 year postpartum (p ≤ 0.010)." (PMID 37891561, 2023). "As written above, insulin resistance is one of the main steps that lead to the development of T2D and it is associated with obesity, a lack of physical activity and aging; in T2D patients, in fact, insulin is not sufficient to act against the high level of glucose consumed during a meal." (PMID 38137918, 2023). "As an alternative, the Homeostatic Model Assessment for Insulin Resistance (HOMA-IR) has been widely used to assess IR, using fasting glucose and insulin levels." (PMID 37775762, 2023). "Previously, we have found reduced expression levels of selected key insulin signaling proteins in adipose tissue from young LBW men, suggesting impaired protein translation and possibly contributing to development of insulin resistance." (PMID 37049431, 2023). "The homeostasis model assessment of insulin resistance (HOMA-IR) is considered another preferential index, which requires the measurement of fasting insulin." (PMID 36890516, 2023). "Homeostasis model assessment insulin resistance index (HOMA-IR) was calculated from fasting glucose and insulin levels." (PMID 37113327, 2023). "As in 3T3-L1 adipocyte models of insulin resistance, the dysregulation of GSK3 in insulin-resistant tissue was due to a combination of altered activity before and after insulin stimulation." (PMID 36808134, 2023). "Using a cross-sectional design, this study confirmed that IL-18 correlated positively with insulin resistance and individuals with a HOMA-IR ≥ 2.5 displayed higher circulating IL-18 levels compared with their insulin-sensitive counterparts." (PMID 37049621, 2023). "It has also been demonstrated that the levels of p38 phosphorylation are increased in type 2 diabetic adipocytes, which downregulate the translocation of insulin stimulated GLUT4, contributing to the insulin resistance." (PMID 37513589, 2023). "The CP group showed statistically significantly insulin resistance with a lower HOMA-%S (p = 0.0003) and a reduced HOMA-%BxS (p = 0.049) despite a higher insulin level (p = 0.01) vs the control group, even after BMI adjustment." (PMID 36651310, 2023). "It has been suggested that insulin modulates CBS activity, and modulation becomes disturbed in insulin resistance." (PMID 37424916, 2023). "● In obese condition, high-circulatory insulin concentration, ATM invasion, and subsequent inflammation in white AT go hand in hand, which establish insulin resistance as an inflammatory disease." (PMID 36718668, 2023). "The insulin resistance index (homeostatic model assessment for insulin resistance [HOMA-IR]) along with GTT and insulin tolerance test (ITT) suggested modest improvements in insulin sensitivity in TcMAC21 relative to euploid mice." (PMID 37249575, 2023).
Insulin resistance (continued). "The glucose intolerance and insulin resistance in patients with T2DM are addressed using various therapies, including dietary plans, and oral agents such as TZDs, Metformin, and insulin." (PMID 37362539, 2023). "Strikingly, these mice also showed profound glucose intolerance (GTT), impaired glucose‐stimulated insulin secretion (GSIS), and insulin resistance." (PMID 37712288, 2023). "Insulin sensitivity in the liver and skeletal muscle was improved in SELENOP-deficient mice, while intraperitoneal injection with SELENOP impaired insulin signaling, suggesting that SELENOP is a hepatokine capable of inducing insulin resistance." (PMID 37895024, 2023). "Developments in phosphoproteomics and methods to interrogate GLUT4 traffic have revealed alterations in both insulin signalling and specific stages of the GLUT4 trafficking pathway in insulin resistance." (PMID 37248992, 2023). "Overall, more models had altered GSK3 activity in the insulin-stimulated state, suggesting that the primary defect of GSK3 regulation in insulin resistance is the inability of insulin to attenuate GSK3 activity." (PMID 36808134, 2023). "These insulin sensitivity indices are impaired not only in patients with secondary DM but also in patients with NGT, suggesting that insulin resistance is the primary pathophysiologic defect of glucose metabolism in acromegaly." (PMID 36882643, 2023). "Compared to the nOb-CRC group, the Ob-CRC group had significantly higher median levels of fasting plasma glucose (FPG, p < 0.01), fasting plasma insulin (FPI, p < 0.01) and the homeostasis model assessment of insulin resistance (HOMA-IR) values (p < 0.01)." (PMID 36806702, 2023). "Nevertheless, insulin signaling inhibits PGC-1α, while its overexpression promotes hepatic insulin resistance." (PMID 36902112, 2023). "The relationship between increased free fatty acids (FFAs) and insulin resistance at cellular level has been recognized from early studies, and our pathophysiological perspective has evolved from Randle hypothesis to the theory of post-receptor inhibition of insulin signaling by FFAs." (PMID 36882643, 2023). "Decreased sensitivity to insulin action is the major feature of T2DM and insulin resistance has also been observed in patients with Alzheimer’s disease." (PMID 38273877, 2023). "β-cell function (HOMA2-β), insulin resistance (HOMA2-IR), and Gutt’s insulin sensitivity index (Gutt-ISI) were also calculated." (PMID 36909323, 2023). "Several studies have shown improved insulin signaling and enhanced GLUT4 translocation following resveratrol treatment in animal models of insulin resistance." (PMID 38027557, 2023). "Given the established links between insulin resistance and the development of NAFLD, it is possible that IGFBP-2 contributes indirectly to a low LF phenotype by enhancing insulin sensitivity despite the presence of visceral obesity." (PMID 37854178, 2023). "Height and body weight, BMI, blood pressure, insulin, glucose, HDL-cholesterol, and homeostasis model assessment-insulin resistance (HOMA-IR) levels were similar in all groups." (PMID 36977405, 2023). "SC males showed a higher index of insulin resistance (189% HOMA-IR; p < 0.05) and lower for insulin sensitivity (9% lower QUICKI; p < 0.01) compared to IC males, with IC females in an intermediate position." (PMID 37627441, 2023). "Given the pivotal role of insulin resistance (IR) in the pathogenesis of PCOS, in the last years, many insulin-sensitizing factors have been proposed for PCOS treatment." (PMID 37513627, 2023). "In contrast to MHO, children with MUO had higher BMI SDS, were more overweight, had higher waist circumference (WC), higher insulin resistance index (HOMA-IR), lower insulin sensitivity, and higher pro-inflammatory markers." (PMID 37038589, 2023). "For determination of insulin resistance, homeostatic model assessment (HOMA) of insulin resistance was calculated [HOMA-IR = FBG (mg/dL) × Insulin (μIU/L)/405]." (PMID 37365247, 2023).
Insulin resistance (continued). "Homeostasis model assessment of insulin resistance (HOMA-IR), was calculated using fasting insulin levels and fasting blood glucose level by appropriate formula." (PMID 36873578, 2023). "Increased OGT in the liver has been reported to inhibit the expression of insulin signaling genes, such as IRS1 and Akt, contributing to insulin resistance." (PMID 36768465, 2023). "The levels of fasting plasma glucose (FPG), glycated hemoglobin A1c (HbA1c), fasting insulin (FINS) and homeostasis model assessment-insulin resistance (HOMA-IR) of T2DM+CP, T2DM and CP groups followed a descending order (P<0.05)." (PMID 38223593, 2023). "To investigate the effects of swimming exercise on glucose metabolism in IR mice, we measured their fasting blood glucose levels (FBG), fasting insulin levels (FINS), and the homeostatic model assessment of insulin resistance (HOMA-IR) index." (PMID 37907845, 2023). "It was shown that formononetin significantly increased insulin sensitivity index, decreased HOMA-IR, and improved insulin resistance." (PMID 36820318, 2023). "According to the homeostasis model assessment of insulin resistance (HOMA-IR), TG-REG3 mice showed lower HOMA scores than WT mice, indicating that TG-REG3 mice improved, and maintained their better insulin sensitivity with advanced age." (PMID 36918710, 2023). "PCOS patients had significantly higher levels of fasting insulin (FINS), hemostasis of model assessment-insulin resistance, low-lipoprotein cholesterol, triglyceride, apolipoprotein B, apolipoprotein B/apolipoprotein A1, and homocysteine than the controls." (PMID 36930082, 2023). "On the contrary, a recent cross-sectional analysis of RISE Study data showed higher insulin secretion rates and β-cell secretion more responsive to glucose in youth with IGT or T2D relative to adults even after adjusting for insulin resistance differences." (PMID 37432389, 2023). "Our previous study demonstrated that acupuncture is capable of improving fasting blood glucose (FBG), plasma fasting insulin (FINS), insulin resistance index (HOMA-IR), and insulin signal molecules in OLETF rats." (PMID 37034166, 2023). "(C) Homeostasis model assessment of insulin resistance (HOMA-IR) was determined from fasting glucose and insulin levels." (PMID 36648330, 2023). "However, the effect of NMN was specific to insulin sensitivity in muscle and did not affect other important variables associated with insulin resistance, including indices of liver and adipose tissue insulin sensitivity, fasting plasma glucose, insulin, and adiponectin concentrations." (PMID 35821806, 2022). "Besides, obesity may also cause the increased cortisol and androgen secretion leading to lower insulin sensitivity in muscle tissue and liver and physical and chronic psychologic stress may play an important role in exacerbating insulin resistance, prediabetes, and T2DM." (PMID 35495951, 2022). "It has been shown that testosterone affects the transmission of post binding insulin signal, reducing both the number and the efficiency of glucose transporters (GLUT-4), contributing to insulin resistance." (PMID 36009471, 2022). "Within this study, in vitro experiments also highlighted that a lack of BVR-A functions is detrimental for cells and drives them toward insulin resistance, while recovering BVR-A activities rescue insulin signalling activation." (PMID 35628384, 2022). "The high FBG, fasting serum insulin (FSI), and HOMA-IR levels were dramatically reduced after treatment with GLE, indicating a reduction in insulin resistance and improved glycemic management." (PMID 35964948, 2022). "In terms of fasting measures, both the homeostatic model assessment of insulin resistance (HOMA-IR) and fasting glucose are reflective of hepatic insulin sensitivity." (PMID 35834023, 2022). "Like other Mφs, BMM1-sEVs enhance insulin resistance; however, BMM2-sEVs enhance insulin sensitivity and reduce glucose intolerance and insulin resistance." (PMID 35832790, 2022).
Insulin resistance (continued). "Obesity and low-grade inflammation induce insulin resistance but a recent study showed that TNF-α inhibited insulin-stimulated glucose uptake in 3T3-L1 cells, while knockdown of BRD2 maintained their insulin sensitivity." (PMID 36015180, 2022). "Insulin sensitivities of the HFD group were impaired compared to the CK group, but kaempferol significantly reversed the insulin resistance induced by high-fat diet." (PMID 35334817, 2022). "Our analysis further confirmed the enrichment of TNF-mediated pathway, insulin resistance, and increased ERK signaling along with downregulation of insulin signaling." (PMID 36012331, 2022). "A decrease in markers for insulin resistance (HOMA-IR), HOMA-B, and insulin secretion, as well as an increase in quantitative insulin sensitivity check index (QUICKI) was found with probiotics compared with placebo." (PMID 35458105, 2022). "Fasting blood glucose (FBG) levels, glucose tolerance and insulin sensitivity in mice fed a HFD or chow for 12 weeks were measured; insulin resistance was more severe in mice fed a HFD for 12 weeks." (PMID 35896788, 2022). "Regarding the effect on insulin resistance, previous studies reported that puerarin and Radix pueraria lobata improved glucose metabolism by reducing FBG and insulin concentrations." (PMID 35052852, 2022). "Our study showed reduced expression of pAkt despite of high serum insulin levels and intracardiac PI3K activity in db/db control mice, suggesting presence of a significant insulin resistance." (PMID 35351872, 2022). "A high fat diet induced insulin resistance, by reducing the expression of IRS-1, which is an important mediator in insulin signal pathway." (PMID 35487948, 2022). "The ablation of MDSC in obese mice enhanced insulin resistance and exaggerated systemic inflammation, whereas the transfer of purified MDSC improved glucose tolerance and insulin sensitivity in obese mice." (PMID 36555392, 2022). "Interestingly, PLIN2 deficiency had a beneficial effect on insulin sensitivity, suggesting that loss of PLIN2 was able to protect against ALD-associated hepatic insulin resistance, an effect that may be secondary to impaired hepatic lipid accumulation in these mice." (PMID 35864895, 2022). "Moreover, BPA-induced insulin resistance in adipocytes was shown to be independent of adipogenesis, being associated with reduced insulin-induced Akt phosphorylation and increased proinflammatory cytokine mRNA levels and being indicative of the role of BPA-induced inflammation in insulin resistance." (PMID 35202251, 2022). "In adipose tissue in obesity, the activation of this pathway results in insulin resistance through IKK-mediated serine phosphorylation of IRS-1 or insulin receptor, leading to the inhibition of insulin-induced serine phosphorylation and downstream signaling." (PMID 36012516, 2022). "In this way, FFA disrupts insulin signaling through toll-like receptor 4 (TLR4) pathway, resulting in insulin resistance (IR)." (PMID 35190756, 2022). "We aimed to explore the causal relationship between tea intake, T2D, and glycemic traits including hemoglobin A1c (HbA1c), fasting plasma glucose (FPG), fasting serum insulin (FSI), and homeostasis model of insulin resistance (HOMA-IR) levels." (PMID 35422845, 2022). "Insulin resistance (homeostasis assessment model-HOMA IR) and oral insulin disposition index (DIo) were calculated." (PMID 36704786, 2022). "The high value of HOMA-IR, blood glucose, serum insulin, and AUC in the HFD group demonstrated that insulin resistance and/or decreased insulin sensitivity occurred." (PMID 36235772, 2022). "The activation of such molecular mediators promotes the disruption of the insulin signaling pathway, mainly by serine phosphorylation of IRS-1 that leads to insulin resistance and a glucose uptake blockade." (PMID 35327570, 2022).